CYP1A1 (cytochrome P450 family 1 subfamily A member 1)
Diseases named in the same sentence as CYP1A1 in open-access papers (continued):
Sharing a sentence is not in itself a finding about the gene and the disease.
lung carcinoma (continued). "In lung cancer patients, 3 variants were identified, CYP1A1*2C (n = 17), CYP1A1*4 (n = 46) and combined CYP1A1*2C/ CYP1A1*4 (n = 4)." (PMID 28074113, 2017). "Similar observations (higher frequency of CYP1A1 m2 (A/G) allele) were reported in lung cancer patients from Korea." (PMID 27090234, 2016). "Further, in the current study, evaluation of the genotypic frequencies in lung cancer patients from Andhra Pradesh have shown a higher frequency and a significant association of CYP1A1 m2 heterozygous ‘AG’ genotype." (PMID 27090234, 2016). "Results showed that CYP1A1 m1 ‘CC’ genotype was significantly associated with lung cancer susceptibility with a 2.3-fold risk, CYP1A1 m2 ‘AG’ gene polymorphisms with 8.8-fold risk and GSTT1 (−/−) genotype demonstrated a twofold risk of disease susceptibility." (PMID 27090234, 2016). "In an Indian population study, a twofold risk of lung cancer was found in individuals displaying variations in the CYP1A1 and GSTM1 genes." (PMID 27090234, 2016). "Further, increased risk of lung cancer in heavy smokers and light smokers with CYP1A1 m1 allele was demonstrated." (PMID 27090234, 2016). "Results of our study are in parallel with the observations made in different populations worldwide, and it is possible that the mutated genotype of CYP1A1 plays an important role in the aetiology of lung cancer in the population of Andhra Pradesh state." (PMID 27090234, 2016). "Association of lung cancer risk with homozygosity of CYP1A1 variant alleles was reported in Chilean and Caucasian populations." (PMID 27090234, 2016). "A study from Kerala in 146 lung cancer patients indicated that CYP1A1 MspI homozygous variant allele and GSTT1 null deletion frequency were significantly higher in smoking-induced lung cancer patients compared with other populations." (PMID 27090234, 2016). "It has been discovered that the polymorphism of CYP1A1 is associated with many cancers, such as lung cancer, esophageal cancer, endometrial cancer, and cervical cancer." (PMID 25928231, 2015). "The CYP1A1 polymorphisms [Ile462Val (rs1048943) and T6235C (rs4646903)] are associated with lung cancer risk, especially for lung SQC in Asian populations." (PMID 25233467, 2014). "We found that CYP1A1 MspI and Ile462Val polymorphisms correlated with increased lung cancer susceptibility." (PMID 24391993, 2013). "Quercetin inhibited the CYP450 enzymes that were activated by BaP, and the relationship between the consumption of onions rich in flavonoids and lung cancer risk was modified by CYP1A1." (PMID 24069431, 2013). "In a previous study, we have observed reduced expression of estrogen in lung cancer patients which was authenticated by the increased expression of IL-6 and high CYP1A1 polymorphism." (PMID 26316937, 2012). "The CYP1A1 MspI allelic variant has been linked to susceptibility to smoking-related cancers, such as oral, colon, breast, and lung cancers." (PMID 22876118, 2012). "In conclusion, the results of our meta-analysis have provided the comprehensive and convincing evidence that CYP1A1 exon 7 polymorphisms are an important modifying factor in determining susceptibility to lung cancer." (PMID 22952673, 2012). "Twelve-one out of 43 studies examined the association of CYP1A1 exon 7 genotype and the risk of different histological types of lung cancer including SCC, AC and SCLC." (PMID 22952673, 2012). "CYP1A1 MspI genetic variations have been indicated to raise risk for lung cancer, cervical cancer, prostate cancer and laryngeal cancer." (PMID 22846179, 2012). "Several studies have shown that the CYP1A1 MspI T6235C polymorphism is associated with an increased lung cancer risk in Asian populations, especially in relation to tobacco smoking." (PMID 23013535, 2012). "Many studies have examined the association between the CYP1A1 Ile462Val gene polymorphisms and lung cancer risk in various populations, but their results have been inconsistent." (PMID 22952673, 2012).
lung carcinoma (continued). "The observation of reduction in estrogen in lung cancer patient's serum is a novel finding and was supported by the high rate of CYP1A1 genetic polymorphism and increased expression of IL-6 in serum." (PMID 26316937, 2012). "Our results should indicate the interaction between CYP1A1 exon 7 gene polymorphisms and smoking in the development of lung carcinoma." (PMID 22952673, 2012). "Shi X, however, noted a greater risk of lung cancer for CYP1A1 MspI and exon 7 polymorphism carriers in a meta-analysis that included only Chinese population in 15 studies." (PMID 22952673, 2012). "We also found that homozygous mutant genotype of CYP1A1 has a higher chance of risk to lung cancer than the homozygous or heterozygous genotype." (PMID 21859547, 2011). "The CYP1A1 IIe/Val genotype which carries a homozygous mutant type has a higher chance of risk to lung cancer than that which carries a homozygous mutant type and a heterozygous type when the GSTM1 carries a null genotype." (PMID 21859547, 2011). "The role of CYP1A1 polymorphism as a predictor of clinical outcome to EGFR-TKIs in patients with advanced lung cancer has very recently been reported." (PMID 22111840, 2011). "Investigations on association between CYP1A1 polymorphisms and lung cancer have yielded equivocal results." (PMID 22206016, 2011). "To further analyze possible effects of the EPHX1 and CYP1A1 SNPs, we estimated their haplotype frequencies and risk imparted towards lung cancer." (PMID 22206016, 2011). "Fourteen out of 64 studies examined the association of CYP1A1 MspI genotype and the risk of different histological types of lung cancer including SCC, AC and SCLC." (PMID 22014025, 2011). "In conclusion, the results of our meta-analysis have provided the comprehensive and convincing evidence that CYP1A1 MspI and exon 7 polymorphisms are an important modifying factor in determining susceptibility to lung cancer." (PMID 22014025, 2011). "In smokers, EPHX1 Tyr113His and SULT1A1 Arg213His polymorphisms reduced the risk of lung cancer, whereas CYP1A1*2A, CYP1A1*2C and GSTP1 Ile105Val imparted increased risk in non-smokers only." (PMID 22206016, 2011). "Our results should indicate the interaction between CYP1A1 MspI and exon 7 gene polymorphisms and smoking in the development of lung carcinoma." (PMID 22014025, 2011). "Shi ×, however, noted a greater risk of lung cancer for CYP1A1 MspI and exon 7 polymorphism carriers in a meta-analysis that included only Chinese population." (PMID 22014025, 2011). "LR and CART analyses even showed a gene-dosage effect for the increased lung cancer risk with the increasing number of variant allele in the CYP1A1*2A polymorphism." (PMID 22206016, 2011). "Many studies have examined the association between the CYP1A1 MspI and exon 7 gene polymorphisms and lung cancer risk in various populations, but their results have been inconsistent." (PMID 22014025, 2011). "al. reported association of CYP1A1*2A variant allele with lung cancer, however after stratification by smoking the association remained confined to non-smokers only." (PMID 22206016, 2011). "Twelve out of 64 studies examined the association of CYP1A1 exon 7 genotype and the risk of different histological types of lung cancer including SCC, AC and SCLC." (PMID 22014025, 2011). "Only CYP1A1-CG haplotype imparted increased risk to lung cancer (OR = 1.49;95%CI = 1.00−2.21,p = 0.04)." (PMID 22206016, 2011). "Odds ratios (OR)* and 95% confidence intervals (CI) for lung cancer risk according to CYP1A1 genotype groups and stratification by histological types." (PMID 20804547, 2010). "The results suggest that CYP1A1 polymorphisms contribute to increase lung cancer susceptibility in an area with an uncommon high incidence rate." (PMID 20804547, 2010). "The CYP1A1*2B allele (carrying MspI and Ile462Val mutations) was strongly associated with high lung cancer risk (OR = 4.59, CI:1.4-12.6, p <0.01)." (PMID 20804547, 2010).
lung carcinoma (continued). "In summary, the results of this initial study show that 2 polymorphisms occurring at the CYP1A1 gene locus (Ile462Val and Thr461Val) increase the risk to lung cancer in our population, and especially to SCLC." (PMID 20804547, 2010). "Polymorphisms in CYP1A1 (chr15q24.1) are the most frequently studied in relation to lung cancer, but results are limited to only a few SNPs (rs4646903, rs1048943, and rs1799814) that are more frequent in Asian than in Caucasian populations." (PMID 19479063, 2009). "In addition, CYP1A1 encodes a member of the cytochrome P450 superfamily of enzymes and is associated with lung cancer." (PMID 38642129, 2024). "CYP1A1, a cytochrome P450 enzyme involved in metabolism of xenobiotics, has been associated with gastric cancer and precancerous gastric cancer as well as lung cancer." (PMID 38274743, 2023). "Moreover, the expression of CYP1A1 gene polymorphism is closely related to the susceptibility of cervical cancer, prostate cancer, childhood acute leukemia, lung cancer, esophageal cancer, and other tumors." (PMID 35677092, 2022). "In the larger sample size, the variant rs1048943 (CYP1A1) shows an association with squamous cell carcinoma, which is indicative of a population-specific effect of the variant on different histological subtypes of lung cancer." (PMID 34272429, 2021). "The variant rs4646903 of the CYP1A1 gene show an association with lung cancer in smokers only." (PMID 34272429, 2021). "The CYP1A1 Ile462Val substitution in the heme-binding domain of exon 7, leads to a concurrent increase in the catalytic activity of the protein and was associated with lung cancer risk." (PMID 34006906, 2021). "CYP1A1 polymorphisms have been linked to lung cancer risk, particularly when in combination with tobacco smoke, pointing to this gene’s important role in tobacco smoke toxicant metabolism and lung cancer etiology." (PMID 30872662, 2019). "Specific gene mutation such as CYP1A1 significantly increased the risk of female lung cancer." (PMID 31641374, 2019). "In addition to CYP1A1, other smoking signals that we identify in this study have also been previously linked to lung cancer." (PMID 30342560, 2018). "Our findings support that CYP1A1 polymorphisms play a role in the pathogenesis of lung cancer." (PMID 28074113, 2017). "These CYP1A1 polymorphisms have been extensively studied with regard to risk of lung cancer." (PMID 28074113, 2017). "Previous study in life-time non-smoking Chinese women reported an elevated risk of lung cancer for both CYP1A1*2B and *2C homozygous genotypes, furthermore, lung cancer risk associated with both polymorphisms was higher in women with lower environmental tobacco smoke exposure." (PMID 28074113, 2017). "CYP1A1*2C and *4 variants have generally been associated with moderate to high risk of lung cancer." (PMID 28074113, 2017). "Likewise, in the North and South Indian populations, the association of CYP1A1 polymorphism with lung cancer risk was reported." (PMID 27090234, 2016). "Correlations between lung cancer risk and combinations of CYP1A1, GSTM1 and GSTT1 is of particular interest since these genotypes suggest that alterations in the action of phases I and II enzymes lead to defective metabolism of xenobiotic compounds, thereby potentiating the cancer risk." (PMID 27090234, 2016). "Further, a combination of GSTM1 null genotype with CYP1A1 polymorphisms augmented lung cancer risk." (PMID 27090234, 2016). "Previous meta‐analyses suggest that genetic variation of CYP1A1 rs1048943 and rs4646903 might be associated with increased risks of various cancers, such as lung cancer 25 and oesophageal cancer." (PMID 26578427, 2016). "It is widely accepted that tobacco smoking can cause lung cancer, and smoking-induced CYP1A1 gene alterations may contribute to the initiation of lung carcinogenesis." (PMID 27203547, 2016). "A threefold risk of lung cancer associated with CYP1A1 m1 genotype was reported." (PMID 27090234, 2016).
lung carcinoma (continued). "CYP1A1 is involved in metabolism of polycylic aromatic hydrocarbons (PAHs) resulting from tobacco smoking, and these are known to adversely influence lung cancer risk." (PMID 26580635, 2015). "In the human lung, high expression of CYP1A1 has been associated with increased lung cancer risk." (PMID 26629988, 2015). "The interaction of CYP1A1 (Msp1) with mt/mt genotype and GSTM1 null genotype could enhance the risk of lung cancer, and the OR of which were a little higher than the other two CYP1A1 (Msp1) genotypes with GSTM1 null." (PMID 25036724, 2014). "In Caucasians the variant CYP1A1 Val/Val genotype was suggested to be associated with a higher risk of BC, whereas in Chinese and Japanese this amino acid substitution was associated with other types of cancer, as lung cancer." (PMID 24629213, 2014). "Quiñones and Lucas reported that people carrying CYP1A1 polymorphism could be more susceptible to lung cancer induced by environmental pollutants." (PMID 23894592, 2013). "This meta-analysis suggests that the Ile462Val polymorphisms of CYP1A1 correlate with increased lung cancer susceptibility in Asian and Caucasian populations and there is an interaction with smoking status, but these associations vary in different histological types of lung caner." (PMID 22952673, 2012). "In our study, higher methylation levels were associated with poor survival of lung cancer patients that supports the hypothesis that CYP1A1 may have protective role in cancer progression." (PMID 22768131, 2012). "After detailed studies in a large cohort, serum levels of IL-6, estradiol, and genetic polymorphisms in CYP1A1 gene may also be included as biomarkers for early detection of lung cancer." (PMID 26316937, 2012). "Overall, a significantly elevated risk of lung cancer was associated with 2 variants of CYP1A1 MspI (for Type C vs Type A: OR = 1.26, 95% CI = 1.12-1.42, P = 0.003 for heterogeneity; for types B and C combined vs Type A: OR = 1.20, 95% CI = 1.13-1.28, P = 0.000 for heterogeneity)." (PMID 22014025, 2011). "CG haplotype in CYP1A1 was significantly associated with risk of lung cancer." (PMID 22206016, 2011). "Individually, CYP1A1*2A polymorphism was significantly associated with increased lung cancer risk (OR = 1.69;95%CI = 1.11–2.59,p = 0.01), whereas EPHX1 Tyr113His and SULT1A1 Arg213His conferred reduced risk (OR = 0.40;95%CI = 0.25–0.65,p<0.001 and OR = 0.51;95%CI = 0.33–0.78,p = 0.002 respectively)." (PMID 22206016, 2011). "Our data were consistent with the primary results of a previous meta-analysis that showed the MspI and Ile-Val polymorphism of CYP1A1 was a risk factor associated with increased lung cancer susceptibility and these associations varied in different ethnic populations." (PMID 22014025, 2011). "This study was designed to determine whether genetic polymorphisms in the CYP1A1 gene, an activator of carcinogens present in tobacco smoke, could play a role in the extremely high lung cancer incidence rate observed in a rural region of Southern Spain." (PMID 20804547, 2010). "We then tried to determine whether these particularities regarding the presence of CYP1A1 variants were translated into different susceptibilities to lung cancer in our population." (PMID 20804547, 2010). "These CYP1A1 polymorphisms have been extensively studied with regard to lung cancer risk." (PMID 20804547, 2010). "However, the T606G polymorphism has been associated with lung cancer, hormone-dependent tumors, and with the level of sex hormones, which are substrates of CYP1A1." (PMID 22649665, 2010). "Moreover, the association between CYP1A1 rs2606345 genotype and lung cancer was significantly modified by intensity of cigarette smoking, suggesting an underling dose-response mechanism." (PMID 19479063, 2009).
lung carcinoma (continued). "However the results of a case-control study conducted in Rio de Janeiro showed that polymorphism of the Cyp1A1 gene, encoding for an enzyme involved in the metabolism of tobacco carcinogens, was associated with lung cancer risk." (PMID 11994771, 2002). "Genotyping of rs1048943/CYP1A1 that presented significant heterogeneity (p < 0.1) revealed an association with adenocarcinoma among eastern Indian smokers, while a global meta-analysis in 10458 cases and 10871 controls showed association with lung cancer and its subgroups." (PMID 34272429, 2021). "Thus, our case–control study reveals rs1048943/CYP1A1 as a histological subtype-specific variant for lung cancer in the East Indian population, potentially targeting personalised therapy and histology-specific drug designing for lung cancer patients." (PMID 34272429, 2021). "The association of rs1048943 (CYP1A1) across various populations identifies the relevance of the variant in lung cancer risk in a population-specific manner, which could be critical in designing personalised treatment and precision medicine for patients of diverse populations." (PMID 34272429, 2021). "Interestingly, significant effect modification of del1 of the GSTT1 gene and rs4646903 of the CYP1A1 gene on lung cancer by smoking was observed by meta-regression analysis, which suggested the importance of the variants in modifying the risk of lung cancer by smoking status." (PMID 34272429, 2021). "Moreover, we have shown for the first time that Thr461Val (CYP1A1*4) may be by itself a lung cancer risk factor in Caucasians." (PMID 20804547, 2010). "Therefore, if inhalation of coal dust changes PAH-induced CYP1A1 activity, this could modify lung cancer risk." (PMID 19650907, 2009). "Single-nucleotide variations (SNVs) of CYP1A1 at position 4885 have been detected in various lung cancer cell lines using Sanger sequencing." (PMID 40175891, 2025). "In lung cancer, CYP1A1 A-to-I RNA editing drives carcinogenesis through the CYP1A1-HO-1-PI3K/Akt axis, while edited miR-411–5p represents a potential target for reversing TKI resistance by targeting MET." (PMID 41446042, 2025). "Elevated CYP1A1 inducibility is linked to pulmonary PAH-related DNA adduction and an increased risk of lung cancer." (PMID 40559957, 2025). "Our findings indicated that CYP1A1 exhibited higher A-to-I editing levels in 95D highly metastatic lung cancer cell compared with other cell lines, suggesting a potentially pivotal role of this A-to-I RNA edited site of CYP1A1 in cancer progression." (PMID 40175891, 2025). "Association between gene-level methylation scores (AHRR*, MYO1G, CYP1A1, FRMD4A, and GFI1*) and lung cancer risk, among ever smokers (186 matched pairs) nested in the CLUE II cohort (1989–2018)." (PMID 39544416, 2024). "Here, we further demonstrated that overexpressions of XRCC1 and CYP1A1 enhanced the viability, proliferation, migration, and invasion of lung cancer cells through regulating related genes." (PMID 33500536, 2022). "Previous studies have shown that polymorphisms in CYP1A1 and GSTM1 and EGFR contribute to the increased risk of females for lung cancer." (PMID 32344833, 2020). "The upregulated genes included CYP4F3, IL1RL1, PTGS2, and CXCL8, which are related to inflammation; HKDC1, MYEF2 and CYP1A1, which are related to hepatocarcinoma or lung carcinoma; and SLC7A11 and NEFM, which are related to neuronal damage." (PMID 33247188, 2020). "Intriguingly, while CYP1A1 is hypermethylated relative to smoke exposure in newborn blood, we found a CpG site upstream of the CYP1A1 transcription start site to be hypomethylated in lung cancer adenocarcinoma relative to smoking." (PMID 30872662, 2019). "Epidemiology studies showed that there was an increasing risk of developing lung cancer in cigarette amount dependent manner on both GSTM1 and CYP1A1 gene mutate patients." (PMID 31641374, 2019).